DAND5 (DAN domain BMP antagonist family member 5)
Description:
Antagonist of the extracellular signaling protein NODAL, which is required for correct left-right patterning during embryonic development (By similarity). Antagonist of BMP and TGF-beta signaling. Independently of its role in left-right axis establishment, plays a role during heart development, possibly through the regulation of TGF-beta/Nodal signaling pathway (By similarity). Displays anti-angiogenic activity by inhibiting endothelial sprouting, migration, and proliferation. Once internalized by endothelial cells, may alter their redox and glycolytic balance.
Synonyms: CER2; CKTSF1B3; COCO; GREM3; SP1; FLJ38607; DANTE; DTE; CERL2; CRL2; HTX13
Tractability: Antibody: UniProt places it where antibodies can reach, with high confidence; UniProt predicts a signal peptide or a membrane-spanning region; its Gene Ontology location is reachable by antibodies, with medium confidence.
Gene: Protein-coding gene on chromosome 19 (12,965,159 to 12,974,760, forward strand). Ensembl gene ENSG00000179284.
Subcellular location: Secreted
Subcellular location (Human Protein Atlas): Mitochondria; Predicted to be secreted
Pathways (Reactome):
Developmental Biology: Regulation of signaling by NODAL; Signaling by NODAL
Gene Ontology:
Molecular function: morphogen activity; nodal binding; protein sequestering activity; receptor ligand inhibitor activity
Biological process: atrial septum development; determination of heart left/right asymmetry; determination of left/right asymmetry in lateral mesoderm; determination of left/right symmetry; negative regulation of BMP signaling pathway; negative regulation of nodal signaling pathway; negative regulation of transforming growth factor beta receptor signaling pathway; nodal signaling pathway; signal transduction involved in regulation of gene expression; ventricular septum development; regulation of signal transduction
Cellular component: extracellular region
Genetic constraint (gnomAD): Loss-of-function variants: 9 observed, 10.23 expected, observed/expected ratio (o/e) 0.88, 90% interval 0.53 to 1.52. The upper end of that interval is the gene's LOEUF score, 1.52, which puts it in group 6 of 6, group 1 being the genes least tolerant of losing a copy. Missense variants: 244 observed, 252.7 expected, observed/expected ratio (o/e) 0.97, 90% interval 0.87 to 1.07. Synonymous variants: 95 observed, 104.31 expected, observed/expected ratio (o/e) 0.91, 90% interval 0.77 to 1.08.
Gene-disease validity (ClinGen):
ClinGen rates the evidence that DAND5 causes each of these diseases.
congenital heart disease (inheritance undetermined): Disputed. A heart disease that is present at birth.
Homologues: Orthologues: chimpanzee DAND5 (99% identical), dog DAND5 (66% identical), mouse Dand5 (61% identical), macaque DAND5 (57% identical), zebrafish dand5 (25% identical), tropical clawed frog dand5 (23% identical). Paralogues in human: CER1 (28% identical).
Diseases named in the same sentence as DAND5 in open-access papers:
DAND5 is named in the same sentence as 16 diseases in open-access papers, as found by Europe PMC text mining. Sharing a sentence is not in itself a finding about the gene and the disease. The quoted sentences say what the papers report.
breast cancer (5 papers, 2016 to 2023). A primary or metastatic malignant neoplasm involving the breast. "Increased expression of DAND5 in breast cancer was associated with poor survival." (PMID 37333824, 2023). "A disease specific role may be played by DAND5 in the tumour associated angiogenesis of breast cancer, which is yet to be investigated." (PMID 37333824, 2023). "On the other hand, both ACVR2B and DAND5 were negatively correlated with EMT in overall breast cancer." (PMID 37333824, 2023). "To validate the clinical significance of DAND5 overexpression in breast cancer, we analyzed the relationship between DAND5 expression and patient disease-free survival." (PMID 26908452, 2016). "When Gao and colleagues found that DAND5, a secreted factor induced dormant breast cancer cells to undergo reactivation in the lung through a gain-of-function cDNA screen, we was highly inspired." (PMID 26908452, 2016). "In the present study, we found that the prognosis of breast cancer patients was closely related with DAND5 expression not only in the cancer tissues but also in the peripheral blood (PB) serums." (PMID 26908452, 2016). "Furthermore, DAND5 expression was much higher in breast cancer tissues than in normal tissues at both mRNA level and protein level." (PMID 26908452, 2016). "Taken together, we speculate that when DAND5 gene was amplified or DAND5 protein was overexpressed in breast cancer, DAND5 could be secreted from the cells into the surrounding and then affect the microenvironment to facility the cancer cell for progression." (PMID 26908452, 2016). "As recent study identified that DAND5 might have important roles in waking dormant breast cancer stem cells in the lung, we further analyzed the data and found that there were 17 patients in 250 tissue array group who finally developed lung metastasis." (PMID 26908452, 2016). "One recent report revealed that DAND5 was involved in the metastasis in breast cancer." (PMID 26908452, 2016). "Based on these results, we speculated that DAND5 could promote the breast cancer cell growth and induce angiogenesis in breast cancer." (PMID 26908452, 2016). "We speculated that the trend of secreted DAND5 was not very coordinated with DAND5 expression in breast cancer cell." (PMID 26908452, 2016).
congenital heart defects (3 papers, 2017 to 2023). "Regardless, in a genetic screening conducted to understand the role of DAND5 in the aetiology of congenital heart disease, a DAND5 c.455G/A non-synonymous variant was identified in patients displaying an array of CHD." (PMID 36831187, 2023). "In conclusion, we report a missense heterozygous variant, in the DAND5 gene of two unrelated Portuguese patients affected with congenital heart defects arising from possible left-right defects." (PMID 28738792, 2017). "DNA from 38 unrelated children with congenital heart defects arising from possible left-right defects and 40 ethnicity- and geographic-matched controls was direct sequenced for the detection of variants in the two exons of DAND5 gene." (PMID 28738792, 2017). "In this work, we provided a hiPSCs model to evaluate the activity of DAND5 during human-based cardiogenesis, contributing to the understanding of congenital heart disease mechanisms." (PMID 36831187, 2023).
liver cancer (2 papers, 2014 to 2020). An epithelial or non-epithelial malignant neoplasm that arises from the liver. "Eight modules are both CNV-TF regulated and CNV-gene enriched, and among these eight CNV-TFs, YY1, MZF1, DAND5, NFYB, ESR1 have been reported in liver cancer development and metastasis." (PMID 24897108, 2014).
Ventricular hypertrophy (2 papers, 2017 to 2023). Enlargement of the cardiac ventricular muscle tissue with increase in the width of the wall of the ventricle and loss of elasticity. "The hearts of Dand5 knockout mice display ventricular hypertrophy with increased ventricular wall thickness, which causes severe cardiac dysfunction." (PMID 36831187, 2023).
breast tumours (1 paper, 2023). "Reduced expression of GDF9 and DAND5 was observed in breast tumours which presented with distant metastasis (P<0.05)." (PMID 37333824, 2023).
cancer (3 papers, 2015 to 2022). A tumor composed of atypical neoplastic, often pleomorphic cells that invade other tissues. "It showed that DAND5 expression in the cancer tissue directly associated with recurrent diseases of BC patients." (PMID 26908452, 2016). "We found as previously observed that DAND5 was more commonly upregulated in basal cancers and downregulated in Her2 amplified cancers." (PMID 26274893, 2015). "As DAND5 is a secreted BMP inhibitor, we speculated that the secreted DAND5 might affect the capillary network from the surrounding host tissue, which is needed both in cancer proliferation and in cancer metastasis." (PMID 26908452, 2016).
tumor (3 papers, 2016 to 2023). "In addition, other BMP-antagonists, including Dand5 and noggin, have been linked to tumor progression and metastasis." (PMID 31694641, 2019). "Furthermore, secreted DAND5 promoted tumor growth and angiogenesis in vitro and in vivo." (PMID 26908452, 2016).
DAND5 also shares sentences with these, for which no sentence is quoted: avian influenza (1 paper); colorectal cancer (1); dilated cardiomyopathy (1); Heart Disease (1); hypertrophic cardiomyopathy (1); infection (1); Newcastle disease (1); situs inversus (1); uterine cancer (1).